MKRN1 (makorin ring finger protein 1)
Diseases named in the same sentence as MKRN1 in open-access papers (continued):
Sharing a sentence is not in itself a finding about the gene and the disease.
female sterility (1 paper, 2019). "Mkrn1 was endogenously expressed at high levels in ovaries and Mkrn1 knockout resulted in female sterility." (PMID 31009498, 2019).
gastric cancer (1 paper, 2020). A primary or metastatic malignant neoplasm involving the stomach. "MKRN1 depletion promotes cellular senescence in gastric cancer cell lines, which can be rescued by ARF co-depletion." (PMID 32759846, 2020). "MKRN1 and ARF expression in gastric cancer patients shows an inverse correlation, suggesting that MKRN1-mediated ARF degradation may have an important clinical implication in gastric cancer." (PMID 32759846, 2020).
hyperlipidaemia (1 paper, 2018). "Consequently, HFD-induced hyperlipidaemia was almost completely normalised in MKRN1-null mice, which displayed similar plasma lipid concentrations to those of WT mice fed a standard chow diet." (PMID 30143610, 2018).
male infertility (1 paper, 2022). The inability of the male to effect fertilization of an ovum after a specified period of unprotected intercourse. "Defective spermatozoa with accumulated MKRN1 were noticed in human and bull semen samples associated with male infertility (Sutovsky; unpublished data)." (PMID 35682598, 2022). "However, an increased accumulation of MKRN1 in defective bovine and human spermatozoa was also observed (Sutovsky; unpublished data), thus making MKRN1 a potential candidate of male infertility." (PMID 35682598, 2022).
pilocytic astrocytoma (1 paper, 2020). Pilocytic astrocytoma is a rare subtype of low-grade glioma of the central nervous system characterized by a well circumscribed, often cystic, brain tumor with a discrete mural nodule and long, hair-like projections that extend from the neoplastic astrocytes. "It is nevertheless important to note that the presented BRAF multiplexed assay is not designed to detect other rare fusions involving BRAF that have been reported in pilocytic astrocytomas including FAM131:BRAF, RNF130:BRAF, CLCN6:BRAF, MKRN1:BRAF, GNAI1:BRAF, and GTF2I:BRAF." (PMID 33282733, 2020).
rectal cancer (1 paper, 2025). A primary or metastatic malignant neoplasm that affects the rectum. "Indeed, we observed in rectal cancer tissues from patients who did not response to Oxa-based chemotherapies, MKRN1 expression was elevated while AGC1 was repressed." (PMID 40722058, 2025).
skin cutaneous melanoma (1 paper, 2020). "Interestingly, according to the online cancer transcriptome database Oncomine, MKRN1 is overexpressed in stage 4 human uveal melanoma (UVM) but not in skin cutaneous melanoma." (PMID 31949127, 2020).
staphylococcus aureus infection (1 paper, 2021). An infectious process in which the bacteria Staphylococcus aureus is present. "According to the ROC curve, ASB1, UBB, and MKRN1 can effectively act as potential diagnostic markers for distinguishing samples of Staphylococcus aureus infection from healthy counterparts." (PMID 34852788, 2021). "The expression level of UBB, ASB, and MKRN1 could significantly differentiate between Staphylococcus aureus infection and healthy controls based on the ROC curve." (PMID 34852788, 2021).
steatosis (1 paper, 2018). Increased lipid within the cytoplasm of cells. "Given the suppression of lipogenic gene expression, we further investigated the effect of MKRN1 ablation on HepG2 cellular steatosis induced by free fatty acids (FFAs)." (PMID 30143610, 2018).
sterility (1 paper, 2019). "Although the previous study suggests a role of Mkrn1 in neuroendocrine cells in controlling the timing of pupariation, ovary-enriched expression of Mkrn1 and female specific sterility suggest that Mkrn1 function is autonomously required for normal ovarian function." (PMID 31009498, 2019).
tuberculosis (1 paper, 2022). A chronic, recurrent infection caused by the bacterium Mycobacterium tuberculosis. "Disturbing the interaction between host MKRN1 ubiquitin system and mycobacterial PPE protein might be a potential therapeutic target for tuberculosis." (PMID 35603194, 2022).
cancer (14 papers, 2009 to 2025). A tumor composed of atypical neoplastic, often pleomorphic cells that invade other tissues. "MKRN1, an E3 ubiquitin ligase, is implicated in cancer biology by binding to and triggering the degradation of target proteins." (PMID 40722058, 2025). "MKRN1 is highly associated with tumorigenesis and cancer stemness as an E3 ubiquitin ligase." (PMID 37930832, 2023). "MKRN1 positively regulates biological processes mediated by Wnt/β-linked proteins and plays an essential role in the proliferation, migration, and invasion of cancer cells." (PMID 35799780, 2022). "Regarding the clustering by rows (RBPs), there are two main clusters: the first one (mostly related to AS alterations in adult cancer), the bottom cluster in the plot, includes relevant cancer genes such as MKRN1, DKC1, or PABPC4." (PMID 39595158, 2024). "The presence of PABPC4 and MKRN1 has been observed as the most frequently enriched RBPs in the different types of cancer coherently with the literature, proving the relevance of this approach." (PMID 39595158, 2024). "MKRN1 expression in CRC was analysed using the Cancer Cell Line Encyclopaedia and the Cancer Genome Atlas (TCGA) databases." (PMID 37620897, 2023). "Overall, these findings support a potential tumour-promoting function of MKRN1 in cancer initiation and maintenance." (PMID 37620897, 2023). "Except for USC, MESO, and CHOL, FBXO7 was significantly positively correlated with MKRN1 in the remaining cancers." (PMID 35799780, 2022). "MKRN1 was significantly positively correlated with RAD23A in the remaining cancers except for MESO, LGG, UCS, CHOL, READ, and BRCA." (PMID 35799780, 2022). "Except for UVM, CHOL, UCS, SKCM, MKRN1 was significantly positively correlated with RAD23A in the remaining cancers." (PMID 35799780, 2022). "The cancer cell line HL-60 normally expresses the MKRN1 gene at very low levels and MKRN1 protein levels cannot be detected." (PMID 28588610, 2017). "The presence of serum MKRN1 antibodies (s-MKRN1-Abs) in cancer patients was examined by Western blotting." (PMID 19604354, 2009). "Previous studies have revealed that MKRN1 plays critical roles in progression of various cancers." (PMID 40722058, 2025). "MKRN1 directly interacts with and ubiquitinates Apc, thereby accelerating its proteasomal degradation and positively regulating Wnt/β-catenin-mediated proliferation and metastasis of cancer cells." (PMID 37620897, 2023). "FBXO7, RAD23A, and MKRN1 are significantly associated with CD8+ T cells in CAD and multiple cancers and may act through immune responses in CAD and cancer." (PMID 35799780, 2022). "In addition, we found that FBXO7, RAD23A, and MKRN1 were significantly positively correlated in cardiac tissues and most cancers." (PMID 35799780, 2022). "We next analyzed the correlation between FBXO7, RAD23A, and MKRN1 in different cancers." (PMID 35799780, 2022). "Finally, we confirmed the implication of SOX2-enriched SE in MKRN1 expression of cancer stem cells." (PMID 37930832, 2023). "Tumour tissue was used for IHC analysis, which revealed high MKRN1 and TGF-β1 expression and low SNIP1 and E-cadherin expression in the cancer cells." (PMID 37620897, 2023). "It was found that the expression values of FBXO7 were also significantly and positively correlated with the degree of CD8+ T cell infiltration in several cancers, followed by RAD23A and MKRN1." (PMID 35799780, 2022). "Here, we also validate potency of MEKi treatment against multiple, previously uncharacterized BRAF-fusions that have been discovered in PLGGs, some of which, like MKRN1-BRAF, co-occur in diverse adult cancers." (PMID 29156677, 2017). "MKRN1 expression correlated with the tumour, node, and metastasis (TNM) stage of the tumour, and was significantly higher in patients with stages III–IV than in patients with stages I–II cancer (P < 0.001)." (PMID 37620897, 2023).
cancer (continued). "High MKRN1 levels promote TGF-β signalling through ubiquitination and degradation of SNIP1, thereby facilitating CRC metastasis, and supporting MKRN1 as a CRC pro-cancer factor." (PMID 37620897, 2023). "Furthermore, specific BRAF-fusions are common across multiple adult and pediatric cancers, including KIAA1549-BRAF found in pediatric gliomas, breast carcinoma, and sarcomas, and MKRN1-BRAF in PLGGS, colorectal carcinoma, and head and neck carcinoma." (PMID 29156677, 2017). "FBXO7, RAD23A and MKRN1 may act as hub genes linking CAD and cancer in terms of immunity." (PMID 35799780, 2022). "In three pairs of CRC and adjacent non-tumour tissues, we also measured MKRN1 protein levels, and discovered that its expression was more prominent in the CRC tissues than in the adjoining cancer tissues." (PMID 37620897, 2023).
tumor (13 papers, 2009 to 2025). "The E3 ubiquitin ligase MKRN1 is closely linked to tumour development, but the exact mechanism needs to be elucidated." (PMID 37620897, 2023). "Furthermore, the results suggested that MKRN1 might serve as a diagnostic marker for personalized treatment strategies and a therapeutic target to inhibit tumor growth, metastasis, and overcome drug resistance." (PMID 38480859, 2024). "In the MKRN1-KD and non-target control cells derived xenograft mice, we observed MKRN1-KD cell derived tumors exhibited a significantly repressed growth rate and smaller tumor size, as well as notably improved overall survival." (PMID 40722058, 2025). "Makorin ring finger protein 1 (MKRN1) is an E3 ubiquitin ligase involving the mediation of tumor progression and metabolic disorders by ubiquitinating substrates." (PMID 39742262, 2024). "Functional studies demonstrated that targeting MKRN1 effectively inhibited cell proliferation, migration, and invasion, highlighting its critical role in tumor progression and metastasis." (PMID 38480859, 2024). "Rectal tumour tissues were frozen to explore the MKRN1 expression in CRC and its clinical significance." (PMID 37620897, 2023). "MKRN1 ubiquitin ligase plays a role in the development of various tumours, mediating the ubiquitination of different substrate proteins." (PMID 37620897, 2023). "Another previous study has also shown that MKRN1 expression levels in cervical tissue are proportional to tumor stage or grade of tumor, correlating positively with pAKT and negatively with phosphatase and tensin homolog (PTEN) expression levels." (PMID 26817873, 2016). "While MKRN1 has been proposed to function as an inhibitor of tumour suppressors, the upstream pathways regulating MKRN1 function have yet to be identified." (PMID 26183061, 2015). "Examination of the AKT signal in the tumour lysates revealed that MKRN1 knockdown diminished pAKT in a PTEN-dependent manner, in agreement with our previous observations." (PMID 26183061, 2015). "The injected tumours that contained a retroviral-based MKRN1 short hairpin RNA (shRNA) vector exhibited distinct growth retardation compared with control shRNA vector-infected tumours." (PMID 26183061, 2015). "By crosslinking the transcriptomes of the MKRN1- and AGC1-deficient CRC cells, we identified that DEGs were primarily enriched in pathways related to mitochondrial dysfunction, antioxidant responses, and tumor drug resistance." (PMID 40722058, 2025). "Due to the influence of environmental factor, expression level and target substrates, MKRN1 may have a tumor-promoter or suppressor function." (PMID 39742262, 2024). "Similarly, tHERT and FADD degradation through increased MKRN1 activity leads, respectively, to reduced telomerase activity (and reduced telomere length) and reduced tumour cell apoptosis and necrosis." (PMID 37620897, 2023). "Notably, at 36 weeks of growth, a tumour was found in the left lower limb of one mouse in the MKRN1[+ / +] group." (PMID 37620897, 2023). "Thus, down-regulation of p14ARF MKRN1-mediated degradation results in the inhibition of tumour cell senescence." (PMID 37620897, 2023). "Since the TGF-β pathway plays a vital function in EMT induction, a critical step in tumour invasion and metastasis, we further determined whether MKRN1 affects EMT in CRC cells via TGF-β signalling." (PMID 37620897, 2023). "Notably, the concomitant stable depletion of PTEN completely reversed the tumour growth inhibition achieved by MKRN1 knockdown." (PMID 26183061, 2015). "This elevated expression may, in part, account for the development of serum antibodies, and give a rationale of application of s-MKRN1-Abs as a tumor marker." (PMID 19604354, 2009). "This study reported for the first time that the expression of MKRN1 and SNIP1 in CRC were negatively correlated, confirming that SNIP1 can act as a tumour suppressor and can be modified by MKRN1 ubiquitination at the protein level." (PMID 37620897, 2023).
tumor (continued). "The expression of MKRN1 was increased in CIN and tumours compared with normal cells (P<0.001, one-way analysis of variance (ANOVA) and independent t-test)." (PMID 26183061, 2015). "The expression of pAKT and pmTOR was also higher in CIN and tumours than in normal cells, whereas the expression of PTEN was decreased in CIN and tumour tissue compared with normal cells, suggesting a link between MKRN1 and the PI3K/AKT pathway." (PMID 26183061, 2015). "Furthermore, MKRN1 immunoreactivity was significantly correlated with advanced disease and poor outcome, including the FIGO stage (P=0.018, one-way ANOVA and independent t-test) and tumour grade (P<0.001, one-way ANOVA and independent t-test)." (PMID 26183061, 2015).
infection (4 papers, 2021 to 2025). The state of being infected such as from the introduction of a foreign agent such as serum, vaccine, antigenic substance or organism. "MKRN1 catalyzes K48-linked ubiquitination of Capsid at specific residues (K101, K103, and K104), which facilitates proteasomal degradation of Capsid, suggesting that MKRN1 restricts infection by inducing Capsid degradation." (PMID 40007042, 2025). "On the other hand, it should be noted that our previous study also indicates that PCV2 downregulates the expression of MKRN1 to avoid the MKRN1-mediated Cap ubiquitination and degradation at the late phase of infection, thereby promoting viral replication." (PMID 38394330, 2024). "Recombinant MKRN1 ubiquitinates entire M. tuberculosis in vitro, indicating a new potential role for MKRN1 against mycobacteria, suggesting MKRN1 E3 ligase acts as a defensive effect during pathogens infection." (PMID 35463379, 2022). "Some studies displayed that the high expression of MKRN1 can help host cells to defend against infection by inducing ubiquitination of pparγ that is beneficial to M. tuberculosis growth." (PMID 34852788, 2021). "Surprisingly, the endogenous MKRN1 protein was degraded by proteasomes during the late phase of HAdV-C5 infection in various human cell lines, implying that HAdV may have evolved a mechanism to avoid MKRN1-mediated host defensive strategies to benefit their replication." (PMID 35463379, 2022).
metabolic disorders (3 papers, 2019 to 2024). "MKRN1 is an E3 ubiquitin ligase that regulates metabolic diseases and malignancies through the ubiquitination of substrate proteins." (PMID 35463379, 2022).
adenocarcinoma (1 paper, 2020). A common cancer characterized by the presence of malignant glandular cells. "In malignant gastric cancer patients, increased MKRN1 and low ARF expression is observed in well-differentiated adenocarcinoma, while low MKRN1 and high ARF expression is detected in poorly differentiated adenocarcinoma." (PMID 32759846, 2020).
MKRN1 also shares sentences with these, for which no sentence is quoted: polycystic kidney (2 papers); central precocious puberty (1); colorectal tumours (1); head and neck carcinoma (1); Insulin resistance (1); ischemia (1); neuroblastoma (1); ovarian carcinoma (1); renal carcinoma (1); small cell lung carcinoma (1); systemic lupus erythematosus (1); triple-negative breast carcinoma (1); type II diabetes (1); uveal melanoma (1).